TNF (tumor necrosis factor)
Diseases named in the same sentence as TNF in open-access papers (continued):
Sharing a sentence is not in itself a finding about the gene and the disease.
inflammatory bowel disease (continued). "For instance, in inflammatory bowel disease (IBD), an overactive cytokine response leads to chronic inflammation in the gut, driven by excessive production of TNF-α, IL-1β, and IL-6, which contribute to tissue damage and immune dysregulation." (PMID 40364844, 2025). "For severe forms of ulcerative colitis (UC), a chronic inflammatory bowel disease (IBD), biological therapies, including tumor necrosis factor inhibitors (anti-TNF), are often used." (PMID 40414945, 2025). "Inflammatory bowel disease (IBD), including ulcerative colitis (UC), involves chronic gastrointestinal inflammation, with tumor necrosis factor alpha (TNF-α) playing a key role." (PMID 41211505, 2025). "Zwicker and Xu reported that IL-34 might inhibit TNF-α expression in macrophages 1 and overlap with the anti-inflammatory cytokine IL-10-secreting macrophages in inflammatory bowel disease and infectious disease models, suggesting the anti-inflammatory potential of IL-34." (PMID 39883639, 2025). "TNF-α and IL-6 demonstrate strong connections with numerous inflammatory conditions, encompassing inflammatory bowel disease (IBD), rheumatoid arthritis, multiple sclerosis and atherosclerosis (AS)." (PMID 41190345, 2025). "We also explored TNF blockade, a treatment known for its efficacy in inflammatory bowel disease (IBD)." (PMID 41116055, 2025). "Similarly, gingerol from Zingiber officinale (ginger) acts on peripheral nerves to reduce gut hypersensitivity, and curcumin from Curcuma longa (turmeric) inhibits inflammatory mediators such as cyclooxygenase‐2 and TNF‐α, offering benefits for inflammatory bowel disease (IBD) and related disorders." (PMID 41416253, 2025). "Some phages have been shown to reduce pro-inflammatory cytokines such as IL-6, TNF-α, and IL-1β, thus alleviating systemic inflammation in diseases like inflammatory bowel disease (IBD) and rheumatoid arthritis." (PMID 40427029, 2025). "Salivary biomarkers as calprotectin, lactoferrin, and cytokines as TNF and IL-6 can be used to track inflammatory bowel disease (IBD), which indicates damage to the intestines and systemic inflammation." (PMID 40005360, 2025). "Utilizing a proinflammatory cocktail of TNF-α, IL-6, and IL-1β to mimic the inflammatory environment of inflammatory bowel disease (IBD), we observed clear differences in the cellular responses to acute versus chronic inflammation." (PMID 39489847, 2024). "Medications including some antibiotics, TNF inhibitors, and antithyroid agents and systemic diseases such as systemic lupus erythematosus, juvenile dermatomyositis, juvenile idiopathic arthritis, sarcoidosis, inflammatory bowel disease, and malignancy are also major contributors to TA." (PMID 39204132, 2024). "Due to its implication in promoting inflammatory pathologies, such as inflammatory bowel disease (IBD), obesity-related type 2 diabetes, and cancers, the pathological properties of TNF have been particularly well studied." (PMID 39020148, 2024). "Butyrate can decrease pain sensation and TNF-α levels in experimental models and its administration in patients suffering from inflammatory bowel disease (IBD) abdominal pain can relieve pain sensation." (PMID 39063241, 2024). "Anti-tumour necrosis factor [TNF] treatment failure in patients with inflammatory bowel disease [IBD] is common and frequently related to low drug concentrations." (PMID 37551994, 2024). "Biological anti-TNF agents have been considered as a viable therapeutic option for individuals with moderate-to-severe inflammatory bowel disease (IBD)." (PMID 38256689, 2024).
inflammatory bowel disease (continued). "B. acidifaciens may contribute to lower levels of IL-6 and TNF-α, promotion of IgA production, improvement of intestinal immune function, protection against intestinal pathogens, and reduction of the incidence of inflammatory bowel disease." (PMID 38783703, 2024). "Following this study, Th17 cells producing TNFα are suggested to relate to OC differentiation inducing among inflammatory bowel disease (IBD) patients." (PMID 38436712, 2024). "In the area of inflammatory bowel diseases (IBD), a group of chronic autoimmune disorders affecting the digestive tract, the introduction of monoclonal antibodies (MAbs) targeting TNF-α marked a significant advancement." (PMID 38424496, 2024). "In addition, KEGG analysis revealed multiple pathways, including cytokine-cytokine receptor interactions, inflammatory bowel disease, Toll-like receptor signaling pathway, Th1 and Th2 cell differentiation, TNF-α signaling pathway, NOD-like receptor signaling pathway, and chemokine signaling." (PMID 39346531, 2024). "The advent of anti–tumor necrosis factor α (anti-TNFα) therapies has revolutionized the management of chronic inflammatory bowel disease (IBD)." (PMID 38957691, 2024). "Increased production of pro-inflammatory cytokines, including interferon gamma (IFN-γ), TNF-α, IL-1 and IL-13 further exacerbate damage to the intestinal mucosa, as occurs in inflammatory bowel disease (IBD)." (PMID 39273791, 2024). "Tumor necrosis factor-α (TNF-α) inhibitors were the first biologic drugs approved for the treatment of inflammatory bowel disease (IBD)." (PMID 38338289, 2024). "Efficacy of anti-TNF agents in PASH resolution may be related to the underlying connection between pyoderma gangrenosum (PG), hidradenitis suppurativa (HS), and inflammatory bowel disease (IBD), and can optimally be used to manage both conditions with only one medication." (PMID 38878169, 2024). "Antitumor necrosis factor (anti-TNF) biologics have revolutionized the treatment of inflammatory bowel disease (IBD)." (PMID 39525292, 2024). "The advent of anti–tumor necrosis factor α (anti-TNFα) has revolutionized the treatment of inflammatory bowel disease (IBD)." (PMID 38957691, 2024). "Lastly, an anonymous TNF inhibitor was used to treat inflammatory bowel disease (IBD) in a patient, resulting in psoriatic CA of the scalp and asymptomatic plaques on the body." (PMID 38335182, 2024). "Although there are various reports on the evaluation methods, the frequency of primary failure of anti-TNF-α antibody preparations in inflammatory bowel disease (IBD) is approximately 10%–40% overall." (PMID 38166010, 2024). "The introduction of anti-tumor necrosis factor (TNF) alpha agents has significantly transformed the prognosis for patients with inflammatory bowel disease (IBD), resulting in higher remission rates and an enhanced quality of life." (PMID 39410544, 2024). "TNF-α can damage the intestinal barrier function and exacerbate intestinal inflammatory response, and anti-TNF therapies are of great significance for the prevention and control of intestinal inflammatory diseases, such as inflammatory bowel disease (IBD)." (PMID 39334766, 2024). "We used genetic mouse models and noninflamed samples from patients with inflammatory bowel disease (IBD) undergoing anti-TNF therapy to assess the effect of in vivo perturbation of TNF." (PMID 37643009, 2023). "Using inflammatory bowel disease (IBD) as an example application, we show that administration of anti-TNFα siRNA-loaded mEVs reduced inflammation in a rat model of IBD." (PMID 37924132, 2023). "Using inflammatory bowel disease (IBD) as an example application, we show that administration of anti-tumour necrosis factor alpha (TNFα) siRNA-loaded mEVs reduced inflammation in a IBD rat model." (PMID 37924132, 2023). "Tumor necrosis factor-alpha (TNF-α) agonists revolutionized therapeutic algorithms in inflammatory bowel disease (IBD) management." (PMID 37383609, 2023).
inflammatory bowel disease (continued). "After the failure of the initial anti-TNF-α treatment in an inflammatory bowel disease (IBD) patient, the next step involves choosing between a second anti-TNF-α or a drug with a different mechanism of action." (PMID 38137450, 2023). "CD74 is involved in numerous inflammatory-related disease processes, and recent studies in inflammatory bowel disease (IBD) have shown a strong association between CD74 polymorphisms and the failure of anti-TNF therapy in patients with ulcerative colitis." (PMID 36445632, 2023). "Since TNF is a major proinflammatory cytokine in inflammatory bowel disease (IBD), a chronic immune-inflammatory disease of the gastrointestinal tract, anti-TNF therapy is effective in a proportion of patients." (PMID 37686035, 2023). "Despite the evolution in inflammatory bowel disease (IBD) management during the last 20 years owing to the advent of new advanced therapies, anti-TNF agents still remain the cornerstone of therapy for both Crohn’s disease and ulcerative colitis." (PMID 37048536, 2023). "In inflammatory bowel disease, activated DCs could release the inflammatory cytokines such as IL-6, IL-12 and tumor necrosis factor (TNF-α) by up-regulating the pattern recognition receptors [Toll-like receptor (TLR) 2 and TLR4], MHC class II molecules, and costimulatory molecules (CD40 and CD86)." (PMID 37670381, 2023). "Recent studies, however, concluded that anti-TNF therapy and newer biologics may not increase the risk of new-onset or recurrent cancers in patients with inflammatory bowel disease." (PMID 37685662, 2023). "The existence of several TNF inhibitors (e.g., infliximab, adalimumab, etc.)in the market and the current ongoing clinical trials highlight the clinical importance of this molecule in the treatment of diseases such as systemic rheumatic disease and inflammatory bowel disease." (PMID 38003638, 2023). "Loss of therapeutic response (LOR) due to anti-drug antibodies (ADA) against tumor necrosis factor (TNF) inhibitors is common in patients with inflammatory bowel disease (IBD)." (PMID 36840779, 2023). "Here, we found signaling pathways (leishmaniasis, malaria, inflammatory bowel disease (IBD), chemokine, TNF, and others) that are involved in inflammation, predominantly under Semax treatment, 24 h after tMCAO." (PMID 36553646, 2022). "The outcomes of patients with elderly onset (EO) inflammatory bowel disease (IBD) treated with anti-tumor necrosis factor (TNF) remains uncertain." (PMID 35351986, 2022). "Anti-TNF antibodies are effective for treating patients with inflammatory bowel disease (IBD), but many patients fail to respond to anti-TNF therapy, highlighting the importance of TNF-independent disease." (PMID 35077396, 2022). "The role of SphK1 activity in mediating the TNF-α-induced decrease in IL-10 as well as the decrease in TNF-α itself has important translational implications in other inflammatory disorders, particularly those associated with autoimmune diseases such as inflammatory bowel disease." (PMID 35409108, 2022). "Most interestingly, both the reversible decrease in USM and the recovery of splenic deficiency have been observed in Inflammatory Bowel Disease (IBD) patients treated with anti-TNF." (PMID 36148466, 2022). "In recent years, biological agents, such as anti-TNF-α blockers, have been introduced and have shown efficacy in pediatric patients with inflammatory bowel disease (IBD)." (PMID 36304532, 2022). "Clinically, CRMO shares significant overlap with TNFα-related autoimmune conditions such as spondyloarthritis, psoriasis, and inflammatory bowel disease (IBD)." (PMID 36456962, 2022).
inflammatory bowel disease (continued). "For example, there is a European evidence-based consensus to continue treatment with anti-TNFα for inflammatory bowel disease (IBD) throughout pregnancy, given the risks of IBD also for the fetus, even with an FDA Category B/C designation for this drug." (PMID 35448833, 2022). "Accordingly, patients with inflammatory bowel disease (IBD) receiving an anti-TNF treatment had a 78% reduction in the incidence of PD compared to IBD patients who did not receive this therapy." (PMID 35663989, 2022). "Almost half of patients show no primary or secondary response to monoclonal anti-tumor necrosis factor α (anti-TNF) antibody treatment for inflammatory bowel disease (IBD)." (PMID 35743732, 2022). "As inappropriate neutrophil migration accompanies many diseases including inflammatory bowel disease, glomerulonephritis, allergic asthma, chronic obstructive pulmonary disease, and cancer, this antibody has potential for development as a therapeutic agent, akin to anti-TNF antibodies." (PMID 33953162, 2021). "Therefore, targeted transmembrane TNF may benefit more in clinical inflammatory bowel disease and have more promising treatments." (PMID 33553436, 2021). "For example, EXO of intestinal lumen aspirates of inflammatory bowel disease IBD patients carries pro-inflammatory factors including TNF-α, IL6, and IL8 in levels higher than that of healthy controls." (PMID 34208697, 2021). "It has been clearly demonstrated that the aberrant production of inflammatory cytokines, such as TNF-α, IL-1β and IL-6, often observed in the gut of patients with inflammatory bowel disease (IBD), is a consequence of deregulated NF-κB signaling cascade." (PMID 33652555, 2021). "Most of the data available about TNFα inhibitors, in particular infliximab, use in pregnancy are from studies on inflammatory bowel disease (IBD) patients." (PMID 34122062, 2021). "Safety of maintenance anti-TNF treatment was also reported in cohorts of patients with inflammatory bowel disease (IBD)." (PMID 34803441, 2021). "Inflammatory bowel disease (IBD) management completely changed after the approval by the European Medicines Agency (EMA) of the first anti-tumor necrosis factor (TNF) in 1999." (PMID 34640421, 2021). "The goal of therapeutic drug monitoring (TDM) is to optimize anti-TNF (tumor necrosis factor) biologic treatment in patients with inflammatory bowel disease (IBD)." (PMID 33802816, 2021). "Is there an association between the use of anti–tumor necrosis factor (TNF) therapy and all-cause mortality in a national cohort of patients with inflammatory bowel disease (IBD)?" (PMID 33646314, 2021). "The emergence of TNF (tumor necrosis factor) inhibitors has brought about significant improvements in clinical outcomes for patients with inflammatory bowel disease (IBD) refractory to conventional treatment." (PMID 34095175, 2021). "For example, tumor necrosis factor α inhibitors are used frequently for various autoimmune diseases and could be categorized as primarily rheumatologic or gastrointestinal drugs given their use for inflammatory bowel disease." (PMID 34143189, 2021). "The study aim was to evaluate the serum levels of chemerin in patients with inflammatory bowel disease (IBD), depending on disease severity as well as anti-TNF treatment." (PMID 34640632, 2021). "EXO of intestinal lumen aspirates of inflammatory bowel disease IBD patients carry pro-inflammatory factors including TNF-α, IL6, and IL8 in levels higher than that of healthy controls." (PMID 35011677, 2021). "Of note, TNF-α, IL-1β, and IL-6 are produced by macrophages in different inflammatory conditions, including inflammatory bowel diseases (IBD)." (PMID 34072532, 2021). "Anti-tumor necrosis factor (TNF) antibodies have become an indispensable part in the therapeutic landscape of treating inflammatory bowel disease (IBD) patients." (PMID 34616488, 2021).
inflammatory bowel disease (continued). "Infliximab is an anti-TNF-α monoclonal antibody approved in chronic inflammatory bowel diseases (IBD)." (PMID 34834236, 2021). "Clinical studies have shown that patients with inflammatory bowel disease (IBD) infected with COVID-19 can lead to poor recovery, so anti-TNF-α preparations are recommended." (PMID 34305613, 2021). "The recognition of tumor necrosis factor (TNF) as a key proinflammatory cytokine in Crohn’s disease (CD) and ulcerative colitis (UC) and the subsequent development of biologic drugs targeting TNF have redefined the management of inflammatory bowel disease (IBD)." (PMID 36776674, 2021). "Polymorphisms at the tumor necrosis factor (TNF) superfamily member 15 locus, which encodes the TNF superfamily cytokine commonly known as tumor necrosis factor-like ligand 1A, are associated with susceptibility to inflammatory bowel disease in a range of people." (PMID 31480149, 2020). "The use of therapeutic drug monitoring (TDM) of antitumor necrosis factor (anti-TNF) therapies has become more common for the treatment of inflammatory bowel disease (IBD)." (PMID 32887317, 2020). "The advent of anti-tumor necrosis factor (anti-TNF) agents has revolutionized the treatment of inflammatory bowel disease (IBD), which comprises ulcerative colitis (UC) and Crohn’s disease (CD)." (PMID 33154436, 2020). "Evidence supports therapeutic drug monitoring (TDM) in improving efficacy and cost-effectiveness of anti-TNF therapy in inflammatory bowel disease (IBD)." (PMID 32483692, 2020). "Anti-tumor necrosis factor alpha (TNF-α) antibodies are effective in patients with inflammatory bowel disease (IBD)." (PMID 31968666, 2020). "Infliximab (IFX), a chimeric monoclonal antibody targeting tumor necrosis factor-alpha (TNF-α), has been verified as an effective therapeutic medicine for inflammatory bowel disease (IBD)." (PMID 33163192, 2020). "A vitamin D analog, KH 1060, was shown to significantly increase serum vitamin D levels and decrease TNF-α levels among inflammatory bowel disease (IBD) patients." (PMID 32422882, 2020). "TNF inhibitors have proven to block inflammatory bowel disease (IBD) in Crohn's disease, which proves the role of TNF in this inflammatory disease." (PMID 32914580, 2020). "According to the recent nationwide cohort study, parallel to an increasing use of thiopurines and anti-TNF-alpha antibody in inflammatory bowel disease (IBD) over time, a persistent significant decrease in surgery rates was confirmed." (PMID 31641874, 2020). "Further diseases involving the IL-17C/RE axis include psoriasiform skin lesions in inflammatory bowel disease (IBD) patients under anti-TNF-α treatment, recurrent aphthous ulcers, LPS-induced endotoxin shock, and different forms of cancer." (PMID 32174926, 2020). "This imaging method is already being used in several TNF-α mediated diseases, such as RA, inflammatory bowel disease (IBD) and spondyloarthropathy." (PMID 32760396, 2020). "The intestinal epithelial monolayer, at the boundary between microbes and the host immune system, plays an important role in the development of inflammatory bowel disease (IBD), particularly as a target and producer of pro-inflammatory TNF." (PMID 30728350, 2019). "Monoclonal antibodies directed against tumour necrosis factor-α (anti-TNF) have conventionally been the cornerstone of the treatment of moderate-to-severe inflammatory bowel disease (IBD)." (PMID 31064370, 2019). "TNF-α, a 17 kDa polypeptide produced by macrophages, lymphocytes, and natural killer cells, has been shown to play a major role in the inflammatory process, with high levels being found both in Inflammatory Bowel Disease (IBD) and in rheumatoid arthritis patients." (PMID 31001067, 2019).